MYH9 (myosin heavy chain 9)
Diseases named in the same sentence as MYH9 in open-access papers (continued):
Sharing a sentence is not in itself a finding about the gene and the disease.
Hypernatremia (2 papers, 2025). An abnormally increased sodium concentration in the blood. "Intriguingly, we observe a striking sexual dimorphism in morbidity in female Myh9&10 TAL-cKO mice along with early development of hypernatremia." (PMID 39500539, 2025). "This suggests that male Myh9&10 TAL-cKO mice have more moderate hypernatremia at 12 weeks than the female Myh9&10 TAL-cKO mice, also confirmed by serum sodium measurements." (PMID 39500539, 2025). "While characterization of the mouse model indicates a similar pathological course in both sexes, Myh9&10 TAL-cKO female mice develop hypernatremia earlier than males." (PMID 39500539, 2025). "Female Myh9&10 TAL-cKO mice develop severe hypernatremia at 12 weeks, the time at which they become moribund, with an average serum sodium level of 157.3 ± 0.99 mmol (mean ± SEM) compared to controls at 150.5 ± 0.6 mmol (mean ± SEM)." (PMID 39500539, 2025). "Hypernatremia in Myh9&10 TAL-cKO mice is an unexpected result, as there is a decline in NKCC2 protein expression and apical membrane localization in these mice starting at 9 weeks of age." (PMID 39500539, 2025). "While both sexes overcompensate by activating epithelial sodium channel (ENaC) expression in medullary collecting ducts resulting in hypernatremia, this is initially subdued in male Myh9&10 TAL-cKO mice through higher sodium chloride cotransporter (NCC) expression within the distal nephron." (PMID 39500539, 2025). "Furthermore, higher NCC/pNCC levels at 9 weeks of age in Myh9&10 TAL-cKO male mice fail to explain the delayed onset of hypernatremia observed at 12 weeks of age." (PMID 39500539, 2025). "To determine whether hypernatremia in female and male Myh9&10 TAL-cKO mice was due to distal nephron adaptation, we analyzed the primary DCT sodium chloride cotransporter NCC." (PMID 39500539, 2025). "Loss of hydration could account for hypernatremia; however, we ruled out water loss as we did not observe changes in urine osmolality, water intake, or urine volume in female Myh9&10 TAL-cKO mice at any of the analyzed time points." (PMID 39500539, 2025). "Ultimately, lower NCC/pNCC protein levels at 9 weeks of age do not explain the observed hypernatremia in female Myh9&10 TAL-cKO mice, as lower NCC levels would be predicted to result in lower urinary excretion of sodium." (PMID 39500539, 2025). "Although NCC protein levels are higher in male Myh9&10 TAL-cKO mice, this is not sustained, and eventually ENaC expression is initiated, causing hypernatremia." (PMID 39500539, 2025). "While male Myh9/Myh10 TAL-cKO developed polyuria and polydipsia concurrently with hypernatremia, females exhibited an earlier onset of hypernatremia in the absence of these findings." (PMID 39986266, 2025).
lung squamous cell carcinoma (2 papers, 2015 to 2020). "We analyzed the correlation between MYH9 and the expression of angiogenesis and EMT markers in 549 LUSC (lung squamous cell carcinoma) (1st column), 307 CESC (2nd column), and 565 HNSC (3rd column) in the TCGA database." (PMID 32788880, 2020). "However, the relationships between MYH9 expression and clinicopathological features, and patients’ prognoses need to be further studied in a large number of NSCLC cases at various disease stages as well as in lung squamous cell carcinoma." (PMID 25826333, 2015).
lymphoid cancer (2 papers, 2012 to 2022). "Notably, PTGDS inhibition displayed excellent anti-lymphoma effects in vitro and in vivo study, through MYH9-mediated regulation of Wnt–β-catenin–STAT3 signaling." (PMID 34743203, 2022). "However, transcription of cytoskeletal regulators like MYH9 and MYL9 is elevated in different non-lymphoid cancer cell lines, which depend on MRTFs and SRF for cell spreading, adhesion, and motility." (PMID 22385615, 2012).
MYH9-related disease (2 papers, 2012 to 2014). "Rare mutations in MYH9 cause the syndrome known as MYH9-related disorders (MYH9RD), which includes a variably penetrant podocytopathy characterized by irregular thickening of the glomerular basement membrane (GBM), proteinuria and renal failure." (PMID 24949636, 2014).
osteoarthritis (2 papers, 2021 to 2022). A noninflammatory degenerative joint disease occurring chiefly in older persons, characterized by degeneration of the articular cartilage, hypertrophy of bone at the margins and changes in the synovial membrane. "In addition, circHIPK3 (circBase 000284), derived from mesenchymal stem cells, regulates miR-124-3p and MYH9 to prevent chondrocyte apoptosis and hypertrophy in the IL-1β-induced osteoarthritis model." (PMID 36700234, 2022).
pancreatic ductal adenocarcinoma (2 papers, 2024 to 2025). An infiltrating adenocarcinoma that arises from the epithelial cells of the pancreas. "CircSTX6 regulates the expression of non-muscle myosin heavy chain 9 (MYH9) via the circSTX6/miR-449b-5p and circSTX6/CUL2/HIF-1α pathways, promoting the proliferation and migration of pancreatic ductal adenocarcinoma (PDAC) cells." (PMID 40004471, 2025).
Pancytopenia (2 papers, 2022 to 2025). An abnormal reduction in numbers of all blood cell types (red blood cells, white blood cells, and platelets). "To identify the cause of the pancytopenia in Myh9-deficient mice, we examined hematopoiesis in their BM." (PMID 35740994, 2022). "We found that the loss of Myh9 resulted in severe defects in hematopoiesis, causing pancytopenia, BM failure, and rapid deaths in mice." (PMID 35740994, 2022). "Our data demonstrated that deletion of Myh9 resulted in a comprehensive damage of hematopoiesis, including pancytopenia in peripheral blood, loss of HSPCs with a marked decrease in BM cellularity, and finally caused BM failure and early lethality in Myh9 deficient mice." (PMID 35740994, 2022). "The results showed that deletion of Myh9 led to severe defects in hematopoiesis, characterized by pancytopenia, drastic decreases of hematopoietic stem/progenitor cells (HSPC), and bone marrow failure, causing early lethality in mice." (PMID 35740994, 2022). "Deletion of Myh9 in the recipient animals resulted in marked decrease in BM cellularity and PB counts (pancytopenia)." (PMID 35740994, 2022).
renal fibrosis (2 papers, 2020 to 2025). A final common manifestation of a wide variety of chronic kidney diseases characterized by glomerulosclerosis and tubulointerstitial fibrosis. "The same hypothesis applies to the decreased expression of STMN1, TMSB4X and MYH9 in HK-2 cells under diabetic-like conditions, because: i) STMN1 is a microtubule-destabilizing phosphoprotein whose deficiency in mice has been connected to the development of renal fibrosis." (PMID 32579601, 2020).
retinoblastoma (2 papers, 2012 to 2015). A malignant tumor that originates in the nuclear layer of the retina. "Zbed4 has been reported to interact with estrogen receptor alpha (ERα) and cellular myosin 9 (MYH9) in retinoblastoma cells." (PMID 25692136, 2015). "One of the goals of the present study was to search for binding partners of Zbed4 and here we report the identification of SAFB1, ERα and MYH9 as Zbed4-interacting proteins expressed in Y79 retinoblastoma cells." (PMID 22693546, 2012). "Our experiments also confirmed the nuclear co-localization and possible association of ZBED4 with SAFB1 and ERα and the cytoplasmic interaction of Zbed4 with MYH9 in Y79 retinoblastoma cells." (PMID 22693546, 2012). "We speculate that in Y79 retinoblastoma cells as well as in retina Zbed4 may be transported by the MYH9 trafficking system." (PMID 22693546, 2012). "We also found that Zbed4 interacts in Y79 retinoblastoma cells with nuclear and cytoplasmic proteins Scaffold Attachment Factor B1 (SAFB1), estrogen receptor alpha (ERα), and cellular myosin 9 (MYH9), as shown with immunoprecipitation and mass spectrometry studies as well as gel overlay assays." (PMID 22693546, 2012). "We also found that Zbed4 interacts with nuclear and cytoplasmic proteins and corroborated these results by co-immunoprecipitating Zbed4 from Y79 retinoblastoma cells with the identified proteins, Scaffold Attachment Factor B1 (SAFB1), Estrogen Receptor alpha (ERα) and cellular Myosin 9 (MYH9)." (PMID 22693546, 2012).
Sepsis (2 papers, 2024 to 2025). Sepsis is defined as life-threatening organ dysfunction caused by a dysregulated host response to infection. "In sepsis, MYH9 expression has been linked to altered immune cell dynamics and impaired immune responses." (PMID 40861493, 2025). "The mechanisms by which MYH9 contributes to sepsis pathophysiology remain unclear." (PMID 40861493, 2025). "The six intersection disulfidptosis‐related genes including LRPPRC, SLC7A11, GLUT, MYH9, NUBPL and GYS1 exhibited higher predictive ability for sepsis with an accuracy of 99.7%." (PMID 39400961, 2024). "Our study identified significantly elevated expression of MYH9 in CD4+ T cells, CD8+ T cells, and HSC, as well as in monocytes, neutrophils and NK cells, indicating its potential involvement in the immune dysregulation observed in sepsis." (PMID 40861493, 2025).
sickle cell anemia (2 papers, 2015 to 2020). "In a zebrafish model hypoxia evoked suppression of both the MYH9 and APOL1 genes and the similar nephrogenic effect was induced, while in sickle cell anemia mouse model increased kidney cortex MYH9 expression was found." (PMID 32873246, 2020). "Moreover, in the mouse model of sickle cell anemia ischemic kidney injury modified MYH9 gene and protein expression." (PMID 32873246, 2020).
tongue cancer (2 papers, 2022 to 2026). A malignant neoplasm affecting the tongue. "Notably, tongue cancers in women are reported to exhibit distinct genetic alterations, such as TERT promoter and MYH9 mutations, suggesting that female tongue cancers are clinically and biologically distinct." (PMID 41549073, 2026). "To date, there is no report of a tongue cancer in a young adult with Myosin Heavy Chain 9 (MYH9) mutation." (PMID 35125114, 2022).
acinar cell carcinoma (1 paper, 2021). "In this study, using hybridoma technology, a mouse mAb was generated against MYH9 protein expressed by a human acinar cell carcinoma cell line, Faraz-ICR." (PMID 34425650, 2021). "In our study, only one acinar cell carcinoma tissue was the source of Faraz-ICR cell line, which showed high MYH9 expression intensity as compared with the normal tissue and was used as a positive control to set up the immunohistochemistry." (PMID 34425650, 2021).
autosomal dominant tubulointerstitial kidney disease (1 paper, 2025). "These included 3 cases of autosomal dominant tubulointerstitial kidney disease (UMOD), 3 cases of hereditary FSGS/steroid resistant nephrotic syndrome (INF2 × 2, WT1 × 1), 3 cases of nail-patella-like renal disease (LMX1B), and 2 cases of MYH9-related disease." (PMID 40753325, 2025).
benign prostate hyperplasia (1 paper, 2021). "In PCa cells, the status of MYH9 is also controversial, some studies indicated that MYH9 was significantly upregulated in PCa compared to benign prostate hyperplasia samples through quantitative proteomics." (PMID 33959503, 2021).
brain cancer (1 paper, 2023). A primary or metastatic malignant neoplasm affecting the brain. "To further prove whether GSN-RICTOR and MYH9-RICTOR interactions are associated with cell migrational control, we also determined cell migration ability in two additional cell lines, DBTRG-05MG and SW1088 representing high-grade and low-grade brain cancer cells." (PMID 37120454, 2023).
brain tumor (1 paper, 2021). "Immunofluorescence of mouse brain tumor tissue revealed the same results as IHC of THBS1 and MYH9." (PMID 34635636, 2021).
childhood leukemia (1 paper, 2022). An acute or chronic leukemia that occurs during childhood. "Genetic alterations affecting the process of megakaryopoiesis, such as MYH-9, ETV6, RUNX1, and ANKRD26 variants, have been reported to cause leukemic progression and are especially related to the genetic predisposition of childhood leukemia." (PMID 36534659, 2022).
coagulation disorders (1 paper, 2022). "Myosin-9 plays a crucial role in organelle distribution and F-actin organization in megakaryocytes and platelets and mutations in the MYH9 gene have been related to several coagulation disorders." (PMID 35518205, 2022).
Cognitive impairment (1 paper, 2024). Abnormal cognition is characterized by deficits in thinking, reasoning, or remembering. "In conclusion, our findings suggest that quercetin promotes the proliferation and differentiation of NK cells in peripheral tissues and alleviates cognitive impairment in aging mice by binding to MYH9." (PMID 38730291, 2024).
colitis (1 paper, 2019). Inflammation of the colon. "Blebbistatin protects Lgr5+ stem cells against colitis-induced epithelium injury in gastrointestinal tissues through the Myh9-Rac1-PAK1-Akt pathway and induces cell migration through myosin-II-related matrix stretch and recoil." (PMID 32116554, 2019).
DiGeorge syndrome (1 paper, 2023). "A 22q11.21 microdeletion encompassing the TBX1, SHANK3, SOX10, AP1B1, FBXO7, MYH9, and SPECC1L genes cause DiGeorge syndrome, which is associated with DD, ID, seizure, and cardiac malformations, with a prevalence of 1 in 4000." (PMID 37189911, 2023).
ductal adenocarcinoma (1 paper, 2021). "All of the 21 ductal adenocarcinoma cases were positive for MYH9 cytoplasmic expression with low (n = 9, 42.8%), moderate (n = 10, 47.6%), and high (n = 2, 9.5%) intensities." (PMID 34425650, 2021). "Our results may indicate an increase in the number of ductal adenocarcinoma specimens that show the moderate and high intensity of MYH9 expression in comparison with normal tissues, which signifies the importance of further evaluation in greater sample size." (PMID 34425650, 2021).
Failure to thrive (1 paper, 2025). Failure to thrive (FTT) refers to a child whose physical growth is substantially below the norm. "Female Myh9&10 TAL-cKO mice experience a >20% reduction in body weight by 12-13 weeks of age indicating a failure to thrive phenotype and necessitating euthanization." (PMID 39500539, 2025).
familial cancers (1 paper, 2021).
gastric adenoma (1 paper, 2020). A neoplastic polyp that arises from the stomach. "However, gastric adenomas or carcinomas did not occur in any of these mice during the two years of observation, suggesting that either hMYH9 overexpression or Myh9 knockout in the parietal cells was insufficient to transform gastric epithelial cells into tumors in mice." (PMID 32685004, 2020).
Griscelli syndrome type 1 (1 paper, 2025). A Griscelli syndrome characterized by silvery gray sheen of the hair, hypopigmentation of the skin and neurological impairment without immunodeficiency that has material basis in mutations in the MYO5A gene on chromosome 15q21.2. "Mutations in myosin motors are also associated to many other diseases, including the LRO-transport related diseases Griscelli syndrome Type 1 (GS1) and MYH9 (Myosin9)-related disease." (PMID 40589526, 2025).
hemostatic disorders (1 paper, 2022). "Regardless of the underlying mechanisms, the suppressed compaction of blood clots may be an important pathogenic mechanism for hemostatic disorders with a bleeding tendency in diseases associated with the MYH9 gene mutation." (PMID 36404341, 2022).
IgA nephropathy (1 paper, 2013). "On the other hand, MYH9 rs11089788 was previously associated with high serum creatinine levels in Europeans and with progression of IgA nephropathy in Chinese." (PMID 23516419, 2013).
Infertility (1 paper, 2023). "A recent study reported cytoskeletal abnormalities of Sertoli cells and infertility in male mice with mutations in MYH9." (PMID 36797800, 2023).
invasive lobular carcinoma (1 paper, 2021). "However, MYH9 haploinsufficiency induces invasive lobular carcinoma (ILC) formation." (PMID 33959503, 2021).
ischemia (1 paper, 2020). A hypoperfusion of the BLOOD through an organ or tissue caused by a PATHOLOGIC CONSTRICTION or obstruction of its BLOOD VESSELS, or an absence of BLOOD CIRCULATION. "These emphasize the prominent but functionally unclear role of ischemia on the MYH-9 associated filtration variability." (PMID 32873246, 2020).
liver failure (1 paper, 2012). A liver disease characterized by the liver losing or has lost all of its function. "Indeed, even in MYH9-RD patients of an advanced age, in which an elevation of liver enzymes was detected since the first diagnosis of their disease, there was not one single case developing liver failure." (PMID 22558294, 2012).
liver fibrosis (1 paper, 2023). "In our study, we proposed for the first time that Myh9 was associated with liver fibrosis in NASH; however, the mechanism was unclear." (PMID 36911682, 2023). "In the human liver, the expression levels of Fmnl1 and Myh9 in the MMD system (CCR2/CD68/CD11c+ cells in humans) were also increased with collagen deposition, and the expression levels of Fmnl1 and Myh9 increased with aggravation of the liver fibrosis stage (all p<0.05)." (PMID 36911682, 2023).
metastatic tumours (1 paper, 2020). "On the other hand, clonal mutations in ARNT (OVA_047), NTRK1 (OVA_048), MYH9 (OVA_047) and PPARG (OVA_047), and subclonal mutations in ITGAV (OVA_047) and PTPRT (OVA_003) were all specific to metastatic tumours." (PMID 32099096, 2020).
nephrosis (1 paper, 2025). Pathological processes of the KIDNEY without inflammatory or neoplastic components. "The most severe complication associated with MYH9-RD is nephrosis." (PMID 40416435, 2025).
oral squamous cell carcinoma (1 paper, 2022). "We report the first case of oral squamous cell carcinoma (oSCC) in a young adult with an MYH9-related disorder (MYH9-RD)." (PMID 35125114, 2022).
psychotic disorder (1 paper, 2014). An abnormal condition of the mind that involves a loss of contact with reality. "The genes with a down–up type included SELENBP1, MYH9 and an unnamed gene in chromosome 19, both of which are associated with psychotic disorders." (PMID 25407108, 2014).
renal carcinoma (1 paper, 2012). A carcinoma arising from the epithelium of the renal parenchyma or the renal pelvis. "The association with kidney disorders fits with a high expression of MYH9 that we observed in the NCI-60 renal cancer lines." (PMID 22570691, 2012).
silicosis (1 paper, 2021). Silicosis is a respiratory disease caused by breathing in (inhaling) silica dust. "Our data showed that OC-STAMP interacted with MYH9, which regulated cellular senescence signaling in MLE-12 cells and may have an important role in silicosis." (PMID 34426759, 2021).
soft tissue tumors (1 paper, 2022). "Another point we should address is that MYH9::USP6 was first identified in MO, and the novel USP6 fusion partners UBE2G1 and SNHG3 were uncovered in one case with MO and one case with FO, respectively, expanding our knowledge of USP6-associated soft tissue tumors with bone metaplasia." (PMID 36727055, 2022).
subarachnoid hemorrhage (1 paper, 2024). A serious neurological disorder characterized by intracranial hemorrhage into the subarachnoid space. "However, subsequent studies have reported that some MYH9-RD patients develop cerebral conditions, including subarachnoid hemorrhage." (PMID 39404399, 2024).
transient ischemic attack (1 paper, 2020). A brief attack (from a few minutes to an hour) of cerebral dysfunction of vascular origin, with no persistent neurological deficit. "A 29-year-old female with history of MYH9-RPD, presented to our department for episodes suggesting transient ischemic attacks." (PMID 32950057, 2020).